ERCC1 (ERCC excision repair 1, endonuclease non-catalytic subunit)
Diseases named in the same sentence as ERCC1 in open-access papers (continued):
Sharing a sentence is not in itself a finding about the gene and the disease.
osteosarcoma (13 papers, 2015 to 2024). A usually aggressive malignant bone-forming mesenchymal neoplasm, predominantly affecting adolescents and young adults. "The ERCC1 gene is representative of the nucleotide excision repair genes, which assist osteosarcoma tumour cells in repairing the DNA damage caused by chemotherapy drugs, including cisplatin and cyclophosphamide." (PMID 39335211, 2024). "In our univariate and multivariate analyses of osteosarcomas, the ERCC1 gene in the COS tumour specimens was negatively associated with the chemo-response." (PMID 39335211, 2024). "Two studies 6,7 for the relationship between ERCC1 rs3212986 (8092 C>A) gene polymorphism and osteosarcoma risk were included in this meta-analysis." (PMID 34394247, 2020). "Eight studies 6, 9–15 for the relationship between ERCC1 rs11615 (19007 T>C) gene polymorphism and overall survival of osteosarcoma were included in this meta-analysis." (PMID 34394247, 2020). "Two studies 6,7 for the relationship between ERCC1 rs11615 (19007 T>C) gene polymorphism and osteosarcoma risk were included in this meta-analysis." (PMID 34394247, 2020). "Two studies 9,10 for the relationship between ERCC1 rs2298881 (C>A) gene polymorphism and overall survival of osteosarcoma were included in this meta-analysis." (PMID 34394247, 2020). "Four studies 6, 10–12 for the relationship between ERCC1 rs3212986 (8092 C>A) gene polymorphism and overall survival of osteosarcoma were included in this meta-analysis." (PMID 34394247, 2020). "Several ERCC single nucleotide polymorphisms (SNPs) associated with osteosarcoma prognosis have been reported, including ERCC1 rs11615 (Asn118Asn) and rs3212986 (Gln504Lys), and ERCC2 rs13181 (Lys751Gln) and rs1799793 (Asp312Asn)." (PMID 28977987, 2017). "In conclusion, our meta-analysis indicated that ERCC1 rs11615 is associated with improved osteosarcoma prognosis." (PMID 28977987, 2017). "There existed controversies about the association between the response to chemotherapy for osteosarcoma (OS) patients and the genetic polymorphisms in excision repair cross-complementation group (ERCC1 and ERCC2) genes." (PMID 28388903, 2017). "We conducted an updated systematic review and meta-analysis to investigate associations between ERCC1 and 2 polymorphisms and osteosarcoma prognosis." (PMID 28977987, 2017). "We conducted a systematic review and meta-analysis of ERCC1 and 2 polymorphisms to identify any direct correlations between such polymorphisms and osteosarcoma patient prognosis." (PMID 28977987, 2017). "Therefore, ERCC1 mRNA expression and polymorphisms warrant further investigations in osteosarcoma patients." (PMID 39335211, 2024). "A meta-analysis of six studies in 1137 patients with osteosarcoma suggested that in one Asian population (China), the ERCC1 rs11615 SNP is significantly associated with response to platinum-based chemotherapy, indicating that carriers of the C allele would benefit more from therapy." (PMID 36980706, 2023). "Our results suggested that ERCC1 8092 C allele may play a role as a candidate prognostic marker in patients with osteosarcoma." (PMID 29980176, 2018). "A deficiency in the ability to repair DNA damages could therefore alter the response to treatment with a significant positive association between the polymorphism ERCC2 gene, Lys751Gln, but also ERCC1, Asn118Asn with the improved cisplatin response in osteosarcoma." (PMID 35955506, 2022). "A deficiency in the ability to repair DNA damages could therefore alter the response to treatment with a significant positive association between polymorphism ERCC2 gene, Lys751Gln, but also ERCC1, Asn118Asn with the improved cisplatin response in osteosarcoma." (PMID 35955506, 2022).
osteosarcoma (continued). "The results out of this study, from patients with osteosarcoma treated with cisplatin based neoadjuvant chemotherapy, demonstrated positive association between ERCC1 8092 C allele carriers and better EFS rates in patients with osteosarcoma, suggesting that it may be a good prognostic factor." (PMID 29980176, 2018). "The dysregulated ERCC1 gene in the amputated osteosarcoma tumours suggests its participation in the tumourigenesis, aggressive phenotype, and poor chemo-response." (PMID 39335211, 2024). "Expression of ERCC1, a member of the nucleotide excision repair pathway, has also been correlated with poor survival in osteosarcoma patients." (PMID 32961800, 2020). "ERCC1 (C118T (rs11615) and C8092A (rs3212986)) and ERCC2 (A751C (rs171140) and G312A (rs1799793)) polymorphisms were analysed in 44 patients with osteosarcoma, who were treated with cisplatin based neoadjuvant chemotherapy." (PMID 29980176, 2018). "Our meta-analysis included eleven studies in which four SNPs (ERCC1 rs11615 and rs3212986, ERCC2 rs13181 and rs1799793) reportedly associated with osteosarcoma prognosis were investigated." (PMID 28977987, 2017). "To investigate correlations between excision repair cross-complementation group 1 (ERCC1) and 2 (ERCC2) polymorphisms and osteosarcoma prognosis, we conducted a meta-analysis of studies published through October 2016." (PMID 28977987, 2017). "It was found that pre-treatment osteosarcoma biopsy samples with positive ERCC1 immunohistochemistry had worse prognosis both with regard to event free and overall survivals, and that those being positive for both ERCC1 and ABCB1 had significantly worse prognosis." (PMID 32961800, 2020). "Away from this controversy, the association shown here between ERCC1 C8092A and EFS implies that the patients may be a candidate for further investigation toward using ERCC1 C8092A polymorphisms as a prognostic clinical biomarker, indicating better median EFS rate in osteosarcoma patients." (PMID 29980176, 2018).
head and neck squamous cell carcinoma (11 papers, 2008 to 2023). A squamous cell carcinoma that arises from any of the following anatomic sites: lip and oral cavity, nasal cavity, paranasal sinuses, pharynx, larynx, and salivary glands. "Meta-analysis has shown that ERCC1 expression is associated with the efficacy of platinum-based chemoradiotherapy for head and neck squamous cell carcinoma as well as prognosis of the Asian population; meanwhile, Asians with low ERCC1 expression show better OS and PFS." (PMID 29179456, 2017). "The purpose of this study was to evaluate the role of ERCC1 expression as a predictive marker of survival in patients with locally advanced squamous cell carcinoma of the head and neck (SCCHN) treated with cisplatin-based concurrent chemoradiotherapy (CCRT)." (PMID 18594541, 2008). "The SNAG domain of Snail is essential for both the suppression of E-cadherin and the activation of ERCC1 in head and neck squamous cell carcinoma cells, while in another report, the transactivation of β-catenin-dependent reporter by Snail does not require the SNAG domain but the zinc fingers." (PMID 37380643, 2023). "This study was to evaluate the effect of excision repair cross-complementation group 1(ERCC1) expression on response to cisplatin-based induction chemotherapy (IC) followed by concurrent chemoradiation (CCRT) in locally advanced unresectable head and neck squamous cell carcinoma (HNSCC) patients." (PMID 21426588, 2011). "Co-expression of Snail and excision repair cross-complementing group 1 (ERCC1) in head and neck squamous cell carcinoma (HNSCC) patients correlated with cisplatin resistance and poor prognosis." (PMID 33768509, 2021). "Clinical response to MMC or cisplatin (CDDP)-based radiochemotherapy (RCT) was assessed in 106 head and neck squamous cell carcinoma (HNSCC) patients and correlated with cell nuclear immunoreactivity of the mouse monoclonal (clone: 8 F1) ERCC1 antibody in tumor tissue samples." (PMID 24817012, 2014).
xeroderma pigmentosum group D (11 papers, 2008 to 2023). Any xeroderma pigmentosum in which the cause of the disease is a mutation in the ERCC2 gene. "We studied the usefulness of the excision repair cross-complementing 1 (ERCC1), xeroderma pigmentosum group D (XPD), XRCC1 and GSTP1 polymorphisms as predictors of clinical outcome in these patients." (PMID 18797464, 2008). "In our study group, variation in the ERCC1 (also xeroderma pigmentosum group D - XPD) gene was the third independent factor of treatment responsiveness." (PMID 27527855, 2016). "Our meta-analysis contained 3 genes in NER pathway: ERCC1, xeroderma pigmentosum group D (XPD) and xeroderma pigmentosum group G (XPG)." (PMID 22761669, 2012). "There is also a co-ordinate expression of the xeroderma pigmentosum group D (XPD) with ERCC1 and other genes in the NER repairosome complex." (PMID 18797464, 2008). "The Excision Repair Cross-Complementation group 1 (ERCC1) and xeroderma pigmentosum group D (XPD), which play essential roles in NER, have been found to protect against EC senescence in mice, suggesting a causal relationship between defective NER and vascular aging." (PMID 37894840, 2023). "Like excision repair cross complementing 1 (ERCC1), xeroderma pigmentosum group D and G (XPD, XPG), BRCA1 belongs to nucleotide excision repair (NER) system, which has been reported to be the mayor repair system that reduced platinum-induced DNA damage." (PMID 23497550, 2013). "Three polymorphisms, which are excision repair cross-complementation 1 (ERCC1), xeroderma pigmentosum group D (XPD) and epidermal growth factor receptor (EGFR), were assessed in 257 postoperative stage II/III CRC patients with 5-fluorouracial chemotherapy in Taiwan." (PMID 23429196, 2013). "Downregulation of GLI1 in cisplatin-treated ovarian cancer cells blocked the expression of c-JUN along with excision repair cross-complementing 1 (ERCC1), XRCC1 and xeroderma pigmentosum group D (XPD)." (PMID 26633513, 2015).
cervical squamous cell carcinoma (10 papers, 2012 to 2025). A squamous cell carcinoma arising from the cervical epithelium. "The results showed that ERCC1 118C>T was associated with a high risk of cervical squamous cell carcinomas under the additive genetic model and the dominant genetic model (all P< 0.05)." (PMID 36713431, 2022). "Our study is the first analysis of the association between ERCC1 mRNA expression and treatment response in patients with cervical squamous cell carcinomas who received radical cisplatin-based concurrent chemoradiotherapy." (PMID 23259415, 2012). "FTO‐β‐catenin‐ERCC1 axis can enhance the chemoradiotherapy resistance in cervical squamous cell carcinoma." (PMID 35696608, 2022). "In contrast, decreased m6A in β-catenin mRNA promotes the resistance of cervical squamous cell carcinoma to chemo-radiotherapy by upregulating the excision repair cross-complementation group 1 (ERCC1)." (PMID 33898522, 2021). "We firstly found that cervical squamous cell carcinomas patients with low ERCC1 mRNA level had a significantly higher rate of complete response than patients with high level of ERCC1 expression (P < 0.001)." (PMID 23259415, 2012). "Similarly, improved patient survival and platinum-based chemotherapy TR were observed in cholangiocarcinoma, cervical squamous cell carcinoma, and other tumors with lower ERCC1 levels." (PMID 28977987, 2017). "The purpose of present study was to evaluate whether the ERCC1 mRNA expression levels could predict the treatment response of patients with locally advanced cervical squamous cell carcinoma (LACSCC) who underwent CCCRT." (PMID 23259415, 2012). "However, the association of ERCC1 and treatment response in clinical setting, especially for cervical squamous cell carcinoma, has not be well documented." (PMID 23259415, 2012). "FTO enhances the chemoradiotherapy resistance of cervical squamous cell carcinoma (CSCC) by positively regulating β-catenin expression via mRNA demethylation and in turn increasing excision repair cross-complementation group 1 (ERCC1) activity." (PMID 33162550, 2020). "In cervical squamous cell carcinoma (CSCC), the m6A demethylase FTO promotes resistance to chemoradiotherapy by upregulating β-catenin through mRNA demethylation, which in turn enhances excision repair cross-complementation group 1 (ERCC1) activity." (PMID 41369374, 2025). "It was reported that ERCC1 might act together with class III β-tubulin (TUBB3), which was jointly involved in the development of locally advanced cervical squamous cell carcinoma." (PMID 36713431, 2022). "In cervical squamous cell carcinoma (CSCC), upregulated FTO could promote β-catenin expression via demethylating its transcripts and further positively regulate the excision repair cross-complementation group 1 (ERCC1), contributing to the resistance to cisplatin and irradiation." (PMID 36810281, 2023).
prostate carcinoma (10 papers, 2011 to 2025). A carcinoma that arises from epithelial cells of the prostate gland. "Moreover, a specific nucleotide polymorphism of the ERCC1 gene was linked to prostate cancer aggressiveness in a Spanish cohort study of 494 men." (PMID 28747165, 2017). "The large number of samples in this TMA and the associated database with numerous molecular features allowed us to draw conclusions on the mechanistic role of ERCC1 in prostate cancer." (PMID 28747165, 2017). "Experimental data from a mouse model system suggested an altered ERCC1 function as potential driver for an invasive prostate cancer phenotype." (PMID 28747165, 2017). "For this purpose, a preexisting prostate cancer tissue microarray was examined for ERCC1 expression by immunohistochemistry." (PMID 28747165, 2017). "The strong association of elevated ERCC1 expression with adverse morphological and clinical features of prostate cancer found in this study, argues for a role of ERCC1 overexpression/activation in prostate cancer progression." (PMID 28747165, 2017). "Animal model experiments have suggested a role of the DNA repair protein ERCC1 (Excision Repair Cross-Complementation Group 1) in prostate cancer progression." (PMID 28747165, 2017). "In summary, elevated expression of ERCC1 is strongly linked to unfavorable tumor phenotype and PSA recurrence in prostate cancer." (PMID 28747165, 2017). "In this study increased expression of the DNA repair factor ERCC1 was identified as a strong prognostic marker in prostate cancer, in particular for low-grade tumors." (PMID 28747165, 2017). "The results of our study demonstrate that expression of ERCC1 - a potential surrogate for genomic instability - is an independent prognostic marker in prostate cancer with particular importance in low-grade tumors." (PMID 28747165, 2017). "SNPs rs11615 (ERCC1) and rs17503908 (ATM) appeared as risk factors for prostate cancer aggressiveness." (PMID 25540025, 2014). "Although these three cell lines are all prostate cells, they are at different stages of prostate cancer, and isolated from different tissues, which may contribute to the difference in mRNA expression of ERCC1 among DU145, 22Rv1, and PC3." (PMID 29164150, 2017). "Also, the 12 prostate cancer samples, included in the Human Protein Atlas, showed ERCC1 staining in 83–100% of cases depending on the antibody used." (PMID 28747165, 2017). "The present study evaluates the clinical impact of ERCC1 expression in human prostate cancer." (PMID 28747165, 2017). "ERCC1 may thus represent a surrogate for genomic instability in proliferative active prostate cancer cells." (PMID 28747165, 2017). "However, high-level ERCC1 expression has been reported from the prostate cancer cell lines DU-145 and LNCaP." (PMID 28747165, 2017). "However, data obtained on lymphocytes of prostate cancer patients revealed that carriers of CC genotype showed lower ERCC1 mRNA levels." (PMID 26180747, 2015). "So far, comprehensive studies on ERCC1 expression in clinical prostate cancer samples are lacking." (PMID 28747165, 2017). "That ERCC1 expression failed to provide prognostic information in most subgroups in cancers with comparable quantitative Gleason findings also demonstrates how high the bar lies for prognostic molecular tests in prostate cancer." (PMID 28747165, 2017).
metastatic disease (9 papers, 2008 to 2020). "High ERCC1 mRNA levels in metastatic tumor was associated with a shorter TTF." (PMID 19105824, 2008). "When individual molecular marker expression was analyzed as a possible predictive factor for TTF, those subjects whose metastatic tumor tissue had ERCC1 gene expression above the third quartile had a significantly shorter TTF of 77 days." (PMID 19105824, 2008). "In addition, RRM1 was more highly expressed in primary tumors than metastatic tumors (P = 0.041), while ERCC1 was more highly expressed in metastatic tumors than primary tumors (P = 0.066)." (PMID 26200905, 2015). "The survival advantage in ERCC1- cohort was confirmed in all subgroups and was independent from primary site (pancreatic head or body/tale), number and site of metastases (lymph nodes-limited disease, liver-limited disease, pluri-metastatic disease) and patients' frailty." (PMID 27147577, 2016). "When mRNA expression was compared in paired samples of primary and metastatic tumor tissue, gene expression was significantly higher in metastatic tumor tissue for each molecular marker: TS, 1.9-fold; DPD, 3.8-fold; TP, 1.6-fold; ERCC1, 2.1-fold." (PMID 19105824, 2008). "ERCC1+ and ERCC- cohorts were unbalanced when the number and the sites of metastases were considered (lymph nodes-limited disease, liver-limited disease or pluri-metastatic disease)." (PMID 27147577, 2016).